FTH1 (ferritin heavy chain 1)
Diseases named in the same sentence as FTH1 in open-access papers (continued):
Sharing a sentence is not in itself a finding about the gene and the disease.
cancer (continued). "Our findings offer some valuable insights into the potential of FTH1 in cancer immunotherapy, offering a preliminary analysis of its association with immune cell infiltration, immune molecules, and classical immunotherapeutic markers." (PMID 38281198, 2024). "Our study aims to systematically explore the prognostic significance and immune role of FTH1 in pan-cancers immunotherapy." (PMID 38281198, 2024). "Subsequently, cell-cell communication analysis unraveled that ATF3+CD8T cells and FTH1+NKT occupied most interactions with the cancer cells." (PMID 39238647, 2024). "To investigate the potential role of FTH1 in pan-cancer immunotherapy, we tried to calculate the TIDE score, which is a classical and reliable biomarker for immunotherapy responses, in patients from different expression groups." (PMID 38281198, 2024). "We assessed 19,221 genes and observed a positive correlation between FIN sensitivity and the expression of several well-known NRF2 targets, including NQO1, SLC7A11, GPX2, GCLC, and FTH1, across various cancer cell lines at both the mRNA and protein levels." (PMID 37633973, 2023). "In the MCF7 and in NCI-H460 cells induced epithelial-to-mesenchymal transition (EMT), while in ovarian cancer cells, FTH1 is involved in the inhibition of cancer cell proliferation and in cancer stem cell propagation." (PMID 36361777, 2022). "This study provides a prototype structure for developing MDM4/FTH1 dual-targeting inhibitors as potential cancer therapeutics." (PMID 36431769, 2022). "Although multiple genes, such as ACSL4, PTGS2, NOX1, GPX4, FTH1, and SLC7A11, have been shown to be associated with ferroptosis, it is unclear how ferroptosis is genetically programmed in cancers." (PMID 35321435, 2022). "The aim of this paper was the identification of FTH1 protein partners to further shed light on its functions in cancer cells." (PMID 36361777, 2022). "Previous work has shown that FTH1 expression is increased several human cancers including hepatocellular carcinoma, Hodgkin's lymphoma, and pancreatic cancer." (PMID 34551213, 2021). "Conversely, FTH1 was downregulated in 22 of the 27 cancers (81.5%), upregulated in four cancers (14.8%; CHOL, HNSC, KIRC, KIRP), and unchanged in only one cancer (3.7%; UCEC)." (PMID 33864445, 2021). "In this work, we investigated the effects of X-ray radiation on RR cancer cells in order to determine a possible relationship between FTH1 and LDs." (PMID 34499029, 2021). "We found that high FTH1 expression is positively related to poor prognosis in 11 cancers, including HNSC, which is consistent with our previous study." (PMID 33864445, 2021). "For example, the expression of FTH1 had a positive correlation with drug resistance of cancer cells to Arsenic trioxide, Tamoxifen and Raltitrexed." (PMID 34745224, 2021). "We then selected cancers in which FTL and FTH1 levels were associated with OS at P < 0.001, and performed Kaplan–Meier analysis of OS in patients stratified into high and low expression groups by ROC curve analysis." (PMID 33864445, 2021). "We found that FTL and FTH1 are upregulated and downregulated, respectively, in most of the human cancers analyzed." (PMID 33864445, 2021). "Altogether, these data provide evidence of a new pivotal role for LDs in cancer RR linking their expression with iron metabolism and specifically to FTH1 expression." (PMID 34499029, 2021). "Previous work has shown that c‐MYC increases labile cellular iron availability by repressing FTH1 expression and reducing iron‐storing potential in cancer cells." (PMID 34551213, 2021). "The results suggested that high FTL or high FTH1 mRNA levels were each related to poor OS in several cancer types." (PMID 33864445, 2021). "In contrast to FTL, FTH1 expression was downregulated in 22 and upregulated in four of the 27 cancers examined in our study." (PMID 33864445, 2021).
cancer (continued). "FTH1 levels were positively related to PD-1 in 4/32 (12.5%) cancers, PD-L1 in 9/32 (28.1%), CTLA4 in 7/32 (21.9%), TIM-3 in 20/32 (62.5%), LAG3 in 2/32 (6.3%), and LAIR1 in 19/32 (59.4%)." (PMID 33864445, 2021). "Among these 11 cancers, the FTH1 level was significantly downregulated in nine cancers and significantly upregulated in two (KIRP, HNSC) compared with normal tissues." (PMID 33864445, 2021). "As an MRI reporter, FTH1 alone or in combination with ferritin light chain has been used to monitor cancer cells, stem cells, fibroblasts and dendritic cells." (PMID 27732930, 2016). "These two genes (TfR1 and Fth1) have been previously explored as reporter genes for the MRI of cancer cells and stem cells." (PMID 26184159, 2015). "Therefore, maintaining the proper balance of different FTH1 isoforms is crucial for balancing iron homeostasis and has potential implications for diseases such as cancer, neurodegeneration, and iron-related disorders." (PMID 40507980, 2025). "FTH1 is elevated in a variety of cancers and has antioxidant properties." (PMID 39717847, 2024). "While previous studies have offered preliminary insights into the role of FTH1 in specific cancers, its broader implications in the realm of immunotherapy across diverse cancers remain unknown." (PMID 38281198, 2024). "Curcumin has been proven to modulate TFR1 levels, as well as the two subunits of FT, in cancer cells, ferritin heavy chain (FTH1) and ferritin light chain (FTL), which in turn influences intracellular iron transport and storage functions and alters labile iron levels." (PMID 39309443, 2024). "The heavy chain of ferritin (FTH1) serves as the key modulator in regulating the iron metabolism (Fenton reaction) in ferroptosis, and is concurrently identified as a critical suppressor of this process in numerous cancers." (PMID 38281198, 2024). "Additionally, the differential expression of microRNAs (miRNAs) that regulate FTH1 in cancer cells suggests the potential for designing cancer-specific miRNA mimics or antagomirs to precisely modulate FTH1 expression." (PMID 39294443, 2024). "Nevertheless, the precise impact of FTH1 on cancer immunotherapy remains vague." (PMID 38281198, 2024). "While previous studies have touched upon the role of FTH1 in specific cancers, our investigation is the first to comprehensively explore the relationship between FTH1 levels and immunotherapy response in pan-cancer." (PMID 38281198, 2024). "TCGA analysis indicated that FTH1 played unfavorable prognostic roles in different cancers." (PMID 38281198, 2024). "We found that patients with high FTH1 expression displayed high TIDE scores in most cancers, which may benefit less from immunotherapy treatments." (PMID 38281198, 2024). "Finally, induction of cancer cell ferroptosis by PPI was largely dependent on its regulation of the NRF2/FTH1 pathway." (PMID 37081971, 2023). "Then, the results so far obtained suggested that the interaction between FTH1/PRDX6 in cancer cells might alter cell proliferation and migration, leading to a less invasive phenotype." (PMID 36361777, 2022). "In our studies, FTH1 NCs loaded with DOX could effectively accumulate in the nucleus of cancer cells, in accordance with a previous report." (PMID 35600646, 2022). "Increased expression of FTH1 inhibits cancer by promoting apoptosis." (PMID 36818670, 2022). "Here, we focus on clarifying the new discovers of NCOA4 and FTH1 in cancer." (PMID 34858857, 2021). "In cancer cells, FTH1 is thought to be a bifunctional molecule." (PMID 33864445, 2021). "Moreover, assessing the effects of FTH1 on c‐MYC expression was of particular interest given that the latter is known to downregulate FTH1 expression in cancer cells." (PMID 34551213, 2021). "Finally, the present study shows that both FTL and FTH1 levels are positively correlated with Tregs infiltration in most cancers." (PMID 33864445, 2021). "Previous studies showed a crucial role for FTH1 in cancer aggressiveness." (PMID 34499029, 2021).
cancer (continued). "In the tested cancer cells, piR-FTH1 and Fth1 showed inverse correlation in expression." (PMID 34295823, 2021). "FTH1 silencing downregulates lipid droplets affecting cancer radioresistance." (PMID 34499029, 2021). "To determine whether FTL and FTH1 are differentially expressed in human cancers, we examined expression datasets from TCGA and GTEx databases." (PMID 33864445, 2021). "Furthermore, in combination with our previous study, we continue to develop evidence that FTH1 is an important factor for survival in GICs and a viable target for destruction of cancer cells, including GICs." (PMID 31491006, 2019). "In addition to residing within the cytosol, ferritin can traverse into the nucleus but only FTH1 can interact with DNA where it has been reported to protect corneal epithelial cells from UV radiation and the DNA of some cancer cells from oxidative damage." (PMID 31491006, 2019). "With this innovative reporter gene imaging system, we could not only track cancer cells via MRI as needed but also minimize the potential adverse impacts of continuous FTH1 overexpression and iron accumulation on cell growth." (PMID 27732930, 2016). "Thus, 5 days is not necessarily the optimal duration of in vivo Dox induction for FTH1 expression in cancer cells." (PMID 27732930, 2016). "Notably, FTH1 appears to play a controversial role in the progression of cancer." (PMID 40538534, 2025). "Importantly, FTH1 upregulation appears to play a controversial role in different cancers." (PMID 40538534, 2025). "Our group has shown that LDs are a signature of cancer radioresistance in various cancer cell lines (prostate, lung, breast, bladder, and neuroglioma) and that their intracellular abundance is tightly correlated to iron metabolism, especially to the ferritin heavy chain 1 expression." (PMID 38643120, 2024). "The reason for RAS mutated cancer cells showing high susceptibility to ferroptosis may be that the mutant RAS signals could improve the level of LIP via regulating the iron metabolism related genes expression like FTL, TFRCFTH1 and FTH1." (PMID 39877159, 2024). "On the other hand, FTH1 NCs could specifically bind to cancer cells by interacting with TfR1." (PMID 35600646, 2022). "Interestingly, TIM-3 was positively related to FTL and FTH1 in the most cancers, so does LAIR1." (PMID 33864445, 2021). "Overall, these results provide evidence of a novel mechanism behind RR in which LDs and FTH1 are tightly connected to each other, a synergistic effect that might be worth deeply investigating in order to make cancer cells more radiosensitive and improve the efficacy of radiation treatments." (PMID 34499029, 2021). "Additionally, we have recently shown that in different cancer tissues, including breast, the most radioresistant cancer cells were characterized by a higher LD expression, and that the LD content was tightly regulated by the ferritin heavy chain 1 (FTH1)." (PMID 34576263, 2021). "Within the context of cancer biology, GPX4 serves as a pivotal regulator and central inhibitor of ferroptosis, while FTH1 functions as a crucial iron storage protein." (PMID 40610429, 2025). "IHC staining showed that malignant tumors with high TSPO expression had significantly higher AKR1C1 and FTH1 expression levels." (PMID 40842566, 2025). "Studies have demonstrated that oxidative stress response proteins, including Nrf2, can activate FTH1 and FTL in cancer cells, reducing free iron in the labile iron pool (LIP) and inhibiting ferroptosis." (PMID 40530331, 2025). "Studies on cancer cells with high CAV1 expression have shown that the expression of NOX1 and ACSL4 is increased, and the expression of FTH1 and GPX4 is decreased, which reduces sensitivity to ferroptosis." (PMID 38313306, 2024). "In ovarian cancer, Ferroptosis-related genes (FRGs) that promote ferroptosis, such as FTH1, HIF1A, xCT and GPX4, are greatly correlated with cancer poor prognosis and tumor assoociated macophages (TAMs) infiltration." (PMID 39877159, 2024).
cancer (continued). "The rationale for the selection of the genes, HKDC1, RAB3IL1, RAB39B, FTH1, and FAM213A, is their potential pro-tumorigenic roles in other cancer types." (PMID 37082446, 2023). "Compared with normal tissues, the expression of FRGs with higher amplification frequency increased significantly in cancer tissues (e.g., SQLE, NFS1, and ACACA), and vice versa (e.g., GOT1, HMGCR, and FTH1)." (PMID 35444656, 2022). "So, our findings demonstrate the inhibitory effects of FTH1 on PRDX6 and suggest a new potential therapeutic target for the development of novel therapeutic strategies for the treatments of such cancers overexpressing PRDX6." (PMID 36361777, 2022). "When protein and YM155 were added to NCs at a feed molar ratio of 1:10, the YM155/NP molar ratios in FTH1/YM155 NCs and FTS/YM155 NCs were 1.6 and 1.8, respectively; these formulations had similar cytotoxicity to cancer cells." (PMID 35600646, 2022). "The fourth group, which was consistently identified as cancer by SRS images, contained highly expressed OSCC marker genes including GSTP1, AKR1B10, FTH1, and FTL." (PMID 35776767, 2022). "The FTH1-FTL and LINC02159-ATP10B fusions have previously been reported in the Cancer Cell Line Encyclopedia and TCGA datasets; however, their functions have not been well characterized." (PMID 33809651, 2021). "In contrast, FTH1 overexpression inhibited cell growth, decreased c‐MYC expression, and sensitized cancer cells to chemotherapy; silencing of c‐MYC recapitulated the effects of FTH1 overexpression." (PMID 34551213, 2021). "A similar pattern of correlation between FTH1 and c‐MYC or G9a was observed in 921 cell lines representing different types of human cancer." (PMID 34551213, 2021). "Our previous analysis of diverse cancers found that in HNSCC, FTH1 expression positively correlates with infiltration by macrophages of most solid tumors." (PMID 34527677, 2021). "Through bioinformatics analyses, we demonstrated that the expression of iron-related genes, especially FTH1 and TFRC (which regulate ferritin and the intratumoral iron levels, respectively), were elevated in cancer tissues." (PMID 33204330, 2020). "In particular, two networks directly related to cancer presented MDM2, ICAM1, and FTH1 as central nodes." (PMID 30925701, 2019). "Notably, overexpression of LASS2 reversed the changes in these cancer cells, such as changes in metastasis and ferroptosis-related protein levels (EMT, TFRC, GPX4, FTH1 and FTL1), induced by Fer-1 or erastin." (PMID 38419028, 2024). "Although a lot of experimental evidence suggests that altered expression of FTH1 is a common event in cancer, most of the available studies do not clarify the specific role of FTH1 in this process." (PMID 36361777, 2022). "There have been no previous reports on longitudinal monitoring of cancer cells in vivo using FTH1 in an inducible manner." (PMID 27732930, 2016). "Another important factor in this study was the fact that the cells were treated at confluence for a relatively long time (48 h), and this condition may contribute to the modulation of the expression of at least FTH1, FTL, and TFRC if compared with cells in active proliferation, such as cancer cells." (PMID 41303636, 2025). "The Cancer Genome Atlas (TCGA) and Genotype-Tissue Expression (GTEx) database profiling analysis showed that expressions of ferroptosis suppressors, including SLCA711, GPX4, and FTH1, were also significantly increased in OV compared with healthy ovarian tissues." (PMID 38842940, 2024). "Eleven genes were found to be more essential in cancer cell lines with high expression of MEMO1 (GOF-GIs), six genes were more essential in the cell lines with low-MEMO1 levels (LOF-GIs), and one (FTH1) showed inconsistent types of interactions between different databases." (PMID 38640016, 2024). "Furthermore, FTH1 deletion dramatically inhibited the metastasis and EMT of HNSCC cancer cells." (PMID 38025726, 2023).
cancer (continued). "It is notable that oncogenic RAS-harboring cancer cells (such as HT1080) display increased iron content relative to their normal cell counterparts due to an upregulation of transferrin receptor 1 and downregulation of ferritin heavy chain 1 and ferritin light chain." (PMID 37299622, 2023). "As TFR1 is a receptor for FTH1 as well, and TFR1-mediated internalization of FTH1 is dependent upon a high expression of TFR1, drug molecules could be encapsulated in ferritin cages for delivery directly to cancer cells in a potentially more specific manner than with the previous methods." (PMID 33352721, 2020). "Interestingly, although many ferroptosis regulators such as GPX4, SLC7A11, and FTH1 are obviously increased in certain cancers compared with normal tissues, the treatments targeting these regulators might vary in effectiveness across different cancers." (PMID 38169587, 2024). "Inhibiting Nrf2 in cancer cells leads to decreased expression of NADPH Quinone Dehydrogenase 1 (NQO1), HO1, and ferritin heavy chain (FTH1), which promotes ferroptosis." (PMID 39061859, 2024).